ENSG00000257524 (novel protein)
Gene: Protein-coding gene on chromosome 9 (127,867,850 to 127,906,022, reverse strand). Ensembl gene ENSG00000257524.
Genetic constraint (gnomAD): Missense variants: 307 observed, 423.08 expected, observed/expected ratio (o/e) 0.73, 90% interval 0.66 to 0.8. Synonymous variants: 152 observed, 165.07 expected, observed/expected ratio (o/e) 0.92, 90% interval 0.81 to 1.05.